YY1 (YY1 transcription factor)
Diseases named in the same sentence as YY1 in open-access papers (continued):
Sharing a sentence is not in itself a finding about the gene and the disease.
tumor (continued). "The role YY1 plays as an oncogene or a tumor suppressor in cancers depends on the target gene that it regulates." (PMID 32341359, 2020). "Our findings indicate a critical role of endothelial-specific YY1 in tumorigenesis and suggest endothelial YY1 as a potential target for limiting tumor angiogenesis." (PMID 33235311, 2020). "To elucidate the molecular mechanisms by which YY1 regulates tumor angiogenesis, we used siRNA-mediated YY1 knockdown in human endothelial cells (HUVECs)." (PMID 33235311, 2020). "To investigate the role of YY1 in tumor ECs in vivo, we generated EC-specific YY1 knockout mice by crossbreeding YY1flox/flox with Cdh5-CreERT2 transgenic mice to create YY1iΔEC(Cdh5-CreERT2; YY1flox/flo) mice." (PMID 33235311, 2020). "Over the past decade, studies have shed light on the role of YY1 in the acquisition of various cancer hallmarks in developing neoplasms, which will be detailed in the following sections." (PMID 32226547, 2020). "USP21 promoted NSCLC cell proliferation, migration, and invasion and in vivo tumor growth by stabilizing a well-known oncogene, Yin Yang-1 (YY1), via mediating its deubiquitination." (PMID 31956270, 2020). "Overall, the role of YY1 in tumor metabolic reprogramming contributes to the adaptability of tumor cells to a changing environment." (PMID 32226547, 2020). "The present study revealed that ECs as significant composition in the tumor microenvironment and substantiates the beneficial effects of YY1 depletion against tumor growth." (PMID 33235311, 2020). "Afterward, to validate LINC00668 promoted tumor growth through modulating YY1 expression further, we conducted in vivo experiments." (PMID 32249890, 2020). "YY1 is also an important regulator of mitochondrial metabolism across an array of different cancers, highlighting the importance of tumour YY1 in driving the alterations in mitochondrial communication across the different cells of the tumour microenvironment." (PMID 35582450, 2020). "Numerous studies have shown that YY1 is highly expressed in various tumours and involved in tumour progression by targeting different genes." (PMID 33118286, 2020). "In the present study, we demonstrate a specific role of endothelial YY1 in promoting tumor growth and tumor angiogenesis in vivo." (PMID 33235311, 2020). "In conclusion, our data indicated that YY1 promotes endothelial cell-dependent tumor angiogenesis by promoting VEGFA transcription of HCC in vitro and in vivo." (PMID 31799179, 2019). "Collectively, these findings established that NF-κB/Snail/YY1/RKIP circuitry regulates tumour cell sensitivity to TRAIL-mediated apoptosis." (PMID 31766768, 2019). "In this review, we described YY1 PPIs and their functional implications in tumor growth and suppression." (PMID 31824839, 2019). "While a large body of evidence supports the role of YY1 as a tumor promoter, recent reports indicated that YY1 also functions as a tumor suppressor." (PMID 31824839, 2019). "Although YY1 has been shown to have both tumor promoting and tumor suppressive roles in different cancers, it largely plays a role as a tumor promoter in many cancers." (PMID 31824839, 2019). "Despite its importance as an oncogene, the role of YY1 in tumor cell lipid metabolism remains unraveled." (PMID 31695789, 2019). "AW8507_Tet-ON-shYY1 cells showed a very prominent reduction in tumor growth upon inducible knock down of YY1 with Doxycycline treatment." (PMID 31217904, 2019). "An insight into the mechanism by which YY1 functions as a tumor promoter vs. tumor repressor would help us design novel therapeutic approaches by targeting or manipulating the function of YY1." (PMID 31824839, 2019).
tumor (continued). "Further, YY1 was also shown to repress the tumor suppressor miR-500a-5p and promotes CRC tumor progression in a p300/YY1/HDAC2 dependent manner." (PMID 31824839, 2019). "Our studies demonstrate that miR-500a-5p functions as a tumour suppressor in CRC by targeting the p300/YY1/HDAC2 axis, which contributes to the development of and provides new potential candidates for CRC therapy." (PMID 30737378, 2019). "Such contrasting roles of YY1 both as a tumor promoter and tumor suppressor is puzzling and further work is required to gain a complete mechanistic insight into these opposing functions of YY1." (PMID 31824839, 2019). "Nevertheless, our findings showed for the first time the crucial role of YY1/PGC-1β pathway in tumor cells lipid metabolism." (PMID 31695789, 2019). "Here, the authors investigate the role of miR-500a-5p in CRC in vitro and in vivo models and find that miR-500a-5p acts as a tumour suppressor in CRC by targeting the p300/YY1/HDAC2 axis." (PMID 30737378, 2019). "The results showed that YY1 expressed highly in tumor tissues than normal tissues and upregulated in HCCs with a high degree of malignancy." (PMID 31799179, 2019). "Collectively, these findings together suggested that FAM3C likely initiates the crosstalks among YY1, HSF1 and Akt, finally causing excessive Akt activation to trigger tumour growth and invasion." (PMID 30887707, 2019). "At the end, it is reasonable to argue that the specific nature of YY1 interactome in different cancers would govern the function of YY1 leading to either tumor suppression or tumor promotion." (PMID 31824839, 2019). "While YY1 has been extensively studied for its role in gene regulation (both activation and repression) and cancer, the mechanism by which YY1 contributes to tumor growth differs in different cancers." (PMID 31824839, 2019). "Taken together, depending on its interacting partners and genes that YY1 regulate, it acts as a tumor promoter or suppressor." (PMID 31824839, 2019). "In order to understand the role of CARM1 and YY1 in tumor growth in vivo, xenograft studies were performed in NSG (NOD-SCID gamma) mice." (PMID 31217904, 2019). "Although YY1 is involved in the regulation of tumor malignancy, its role and mechanism in tumor angiogenesis are rarely mentioned." (PMID 31799179, 2019). "In MDV-transformed CD30hi cells, YY1 protein expression was significantly downregulated compared to CD30lo cells indicating a possible tumor suppressant role." (PMID 30764491, 2019). "As YY1 is a positive regulator of tumor cell proliferation, and that lipid accumulation is crucial for tumor cell proliferation, we further investigated the role of YY1/PGC-1β axis in HCC cell proliferation." (PMID 31695789, 2019). "The SDF-1a/CXCR4 signaling has been shown to upregulate YY1 in AML cells in which YY1 downregulates the tumor suppressor microrna miR-let-7a and upregulates MYC and BCLXL to promote AML growth." (PMID 31824839, 2019). "Compared with the control, YY1 overexpression promoted tumor growth, tumor weight and MVD, which indicated by CD31-positive cells." (PMID 31799179, 2019). "In line with this, depletion of YY1 led to impaired tumor formation, colony formation as well as migration whereas overexpression of YY1 resulted in the opposite effect." (PMID 31824839, 2019). "On the contrary, in addition to the opposing functions of YY1 both as a transcriptional activator and repressor, YY1 has also been shown to have two sides in cancer i.e., a tumor promoter and a tumor suppressor." (PMID 31824839, 2019). "While YY1 has been shown to play a key role in the progression of many cancers, the mechanism by which YY1 contributes to tumor growth differs in different cancers by activating or repressing various genes in a cancer specific manner." (PMID 31824839, 2019). "The ability of YY1 to regulate tumor cell lipid metabolism in a HIF-1α-independent manner also provides evidence of the importance of HIF-1α-independent pathways in tumorigenesis." (PMID 31695789, 2019).
tumor (continued). "In accordance to these observations, YY1 is discussed as a biomarker and potential drug target in several tumor types." (PMID 29564133, 2018). "We have shown that RKIP induction in NHL cell lines by the LF-603 αnti-CD20 mAb co-exists with upregulation of the tumor suppressor phosphatase and tensin homologue (PTEN) and Snail/YY1 inhibition, resulting in tumor immune-sensitization." (PMID 30149591, 2018). "Mounting evidence from cancer studies has revealed that YY1 is involved cell cycle regulation, cell proliferation and apoptosis as well as modulation of oncogenes and tumor-suppressor genes expression." (PMID 29470526, 2018). "YY1 was found to be involved in tumor invasion and migration by regulating the epithelial-mesenchymal transition (EMT) process, and YY1 promoted EMT in tumor cells via NF-κB/Snail/YY1/RKIP/PTEN signaling." (PMID 29470526, 2018). "Meanwhile, IHC analysis showed that BMAL1 was negatively associated with miR-135b expression and aggressive parameters of PC, whereas the YY1 level was positively related to pT stage and tumour differentiation." (PMID 29396463, 2018). "The Kaplan–Meier analysis revealed that patients with high miR-135b/low BMAL1/ high YY1-expressing tumours had significantly shorter overall survival (OS) times." (PMID 29396463, 2018). "For example, rituximab inhibited the expression of YY1 resulting in the upregulation of Fas expression and sensitization of the tumor cells to CH-11 (FasL agonist mAb)-induced apoptosis." (PMID 29970878, 2018). "YY1 is overexpressed in multiple cancer types, and its overexpression correlates with poor clinical outcomes, although several studies suggested that in some types of cancer YY1 acts as a tumor suppressor." (PMID 30116722, 2018). "Recent studies showed that YY1-mediated epigenetic silencing of tumor-suppressive microRNAs activated hepatocarcinogenesis and melanoma tumorigenesis." (PMID 28412749, 2017). "In this study, we showed that YY2 demonstrated an expression pattern opposite to YY1 in tumor and normal tissues." (PMID 28903375, 2017). "Specifically, YY1 has been reported to be overexpressed in most MM tumor cells, which leads to the expectation that expression of YY1 and pRKIP would be upregulated in MM." (PMID 28476134, 2017). "Contrary to YY1, which showed a significant increase in tumor tissues, the mRNA expression level of YY2 was robustly decreased." (PMID 28903375, 2017). "The TNF autocrine-paracrine loop induces constitutive activation of transcription factors NF-κB and the transcription repressor YY1 in tumor cells, which both downregulate Fas and induce resistance to FasL-induced apoptosis." (PMID 28476134, 2017). "Consistently, western blotting results demonstrated that the protein expression level of YY2 showed a pattern completely different from that of YY1, as it was lower in tumor tissues than in normal adjacent tissues." (PMID 28903375, 2017). "Immunohistochemical staining results further confirmed these tendencies: compared with normal adjacent tissues, the number of YY1 positive cells was significantly higher in tumor tissues, while the number of YY2 positive cells robustly decreased." (PMID 28903375, 2017). "The TNF-α autocrine-paracrine loop can induce constitutive activation of NF-κB and YY1 in tumor cells." (PMID 28476134, 2017). "For example, several recent studies have found that YY1 modulates tumorigenesis and the development of tumor cells by repressing the expression of numerous miRNAs, including miR-9, miR-29, miR-146a, and miR-489." (PMID 29052509, 2017). "Previous studies have shown that miR-7 functions as a tumor suppresser in CRC by targeting oncogenic YY1 and XRCC2." (PMID 27126129, 2016). "RKIP overexpression appears to regulate tumor cell sensitivity to TRAIL by inhibiting YY1 and up-regulating DR5." (PMID 26177829, 2015).
tumor (continued). "Western blot analysis performed on the expression profiles of the MTOR signal cascade in the tumor adjacent tissues revealed that the treated group expressed a lower level of MTOR/EIF4EBP1/YY1/MYC/SLC2A1 signaling than the untreated group." (PMID 25909713, 2015). "Taken together, these results indicated the tumor suppressive roles of miR-9 in GC cells, which was opposite to its negative regulator YY1." (PMID 26104682, 2015). "The results of the present study regarding the expression of YY1 and its correlation with the tumor grade are consistent with previous findings, which have linked higher YY1 expression to tumors, as compared with benign tissues." (PMID 25174820, 2014). "We thus proposed to study YY1 expression in clinical PDAC samples and the potential mechanisms underlying YY1 mediated tumor progression in PDAC." (PMID 24884523, 2014). "In advanced stage GACs, YY1 nuclear expression correlated with histology with diffuse component (p = 0.020), higher tumor grade (p = 0.033)." (PMID 24674326, 2014). "In the present study, we evaluated the role of YY1 in gastric carcinogenesis and also identified the tumor-suppressive miRNAs modulating gastric carcinogenesis through targeting YY1." (PMID 24970812, 2014). "The β-catenin was effectively knocked down and the same grow suppressive effect was observed, indicating that Wnt/β-catenin signaling pathway plays an important role in the YY1-induced tumor growth." (PMID 24674326, 2014). "Differences (usually overexpression) of YY1 transcript levels in tumor tissue relative to normal counterparts have also been extracted by computational analysis from gene expression omnibus (GEO) datasets." (PMID 24567914, 2014). "In tumor samples, the YY1 expression was directly proportional to the malignant grade, whereby the highest expression was observed in HG PCa as compared with the expression in the LG PCa." (PMID 25174820, 2014). "We have reported that treatment of tumor cells with the NO donor, DETANONOate, resulted in the S-nitrosylation of several proteins including YY1." (PMID 25053986, 2014). "In the present study, it was shown that YY1 was overexpressed in tumor samples as compared with PIN." (PMID 25174820, 2014). "So far, only the Hoxb7 gene expression is positively regulated by YY1 in tumor and transformed cell lines." (PMID 24705708, 2014). "On day 30 postinjection of tumor cells, YY1 mRNA levels in the xenografted tumors of mice after injection with SC-M1 cells transfected with YY1-expressing construct were higher than those of control cells (left)." (PMID 24970812, 2014). "Our data showed that deficiency in tuberin and activation of mTOR resulted in upregulation of YY1 in tumor kidney tissue of TSC patients." (PMID 23705901, 2013). "The inhibition of either Snail or YY1 expression and activity by siRNAs sensitized the tumor cells to CCDP and TRAIL-induced apoptosis." (PMID 23764770, 2013). "Our data clearly demonstrated that both YY1 and RelA are important regulators of MM tumor growth in the xenograft models." (PMID 23874387, 2013). "Here, we report that Yin Yang1 (YY1), a target gene for NF-κB, is hyperexpressed in most MM tumor cells obtained from human patients, exhibits constitutive nuclear localization, and is essential for survival of MM cells." (PMID 23874387, 2013). "In line with its role in survival of MM cells, similar to YY1-depletion, depletion of RelA also has completely impaired MM tumor growth in xenograft model." (PMID 23874387, 2013). "Deficiency in tuberin and increased mTOR activity result in increased the protein expression of YY1 in tumor kidney tissue of patients with TSC." (PMID 23705901, 2013). "To this end, we analyzed the requirement of YY1 for the growth of colony forming MM tumor progenitor cells in semi-solid methylcellulose cultures." (PMID 23874387, 2013).
tumor (continued). "Since both YY1 and RelA are essential regulators of MM tumor cell survival and growth, it is interesting to study additional genes that are either repressed or activated by the RelA-YY1 complex." (PMID 23874387, 2013). "YY1 is highly expressed in primary MM tumor cells derived from human patients as compared to normal human B-cells obtained from healthy donors." (PMID 23874387, 2013). "YY1 was also significantly increased in tumor tissue of AMLs compared to control kidney tissue suggesting that YY1 plays a major role in the regulation of αSMA." (PMID 23705901, 2013). "YY1 can also impact senescence by regulating p16INK4a, and can increase HoxB7 expression directly involved in tumor progression." (PMID 22292011, 2012). "YY1 regulates a large number of genes involved in cell cycle transitions, many of which are oncogenes and tumor-suppressor genes." (PMID 21253604, 2011). "Recently, a dual role of YY1 in cancer development has been suggested, either through over- or under-expression, depending on the tumor type." (PMID 21483740, 2011). "However, YY1 overexpression can inhibit tumor suppressor activity of the retinoblastoma protein (Rb), stimulating cell cycle progression." (PMID 41009346, 2025). "Moreover, the restoration of BH sensitivity in KPUM-YY1R cells through P-gp inhibition confirmed that YY1 drives chemoresistance in tumor cells by upregulating MDR1 gene expression and amplifying drug efflux capacity." (PMID 40867514, 2025). "Collectively, these results suggest that the modulation of YY1 expression in tumor cells could significantly regulate CD8+ T cell activity." (PMID 41322030, 2025). "Moreover, elevated YY1 nuclear expression correlated with reduced survival rate, deeper tumor infiltration, and lymph node metastasis." (PMID 41327312, 2025). "For the first time, our findings highlight YY1 as an independent prognostic factor, indicating that high nuclear YY1 expression in tumor areas measured by DP may serve as a reliable prognostic biomarker in BC." (PMID 41009346, 2025). "Furthermore, low expression of YY1 and BCL2L15 was associated with metastatic disease and worse relapse-free survival, supporting their tumor-suppressive roles." (PMID 41327312, 2025). "Nevertheless, our findings suggest that YY1 could be a more suitable target for enhancing T cell cytotoxicity and inhibiting tumor growth." (PMID 40416970, 2025). "Importantly, we highlight the promising potential of YY1-targeted strategies, particularly combined with anti-tumor agents, to overcome resistance barriers." (PMID 40867514, 2025). "In the tumor cell‐CD8+ T cell coculture system, genetic rescue experiments demonstrated functional restoration of CD8+ T cell activity: knocking down GALNT16 in YY1‐overexpressing tumor cells or overexpressing GALNT16 in YY1‐knockdown cells both reversed YY1‐mediated CD8+ T cell impairment." (PMID 41322030, 2025). "This aberrant phase separation inhibits TBK1 activation, significantly impairs cGAS-STING signaling, and ultimately blocks STING-mediated antitumor immune responses within tumor cells.During PCa progression, upregulated YY1 protein contributes to M2 macrophage polarization." (PMID 40642070, 2025). "Thus, is considered a tumor-suppressor gene whose overexpression has been described to impact the efficiency of the transcription factor YY1, macrophage infiltration, and inflammatory capacity." (PMID 40539042, 2025). "This lactylation enhanced the transcriptional activity of YY1, which led to increased FGF2 expression and might be one of the mechanisms underlying its promotion of tumor angiogenesis." (PMID 41179284, 2025). "Similarly, it was found that YY1 depletion inhibited clonogenicity, migration, invasion, and tumor growth in breast ductal carcinoma samples." (PMID 41327312, 2025). "Our results show elevated median YY1 expression in tumor vs. normal matched tissues (p < 0.001)." (PMID 41009346, 2025).